PLA2G4E (phospholipase A2 group IVE)
Description:
Calcium-dependent N-acyltransferase involved in the biosynthesis of N-acyl ethanolamines (NAEs) in the brain. Transfers the sn-1 fatty acyl chain of phosphatidylcholine (fatty acyl donor) to the amine group of phosphatidylethanolamine (fatty acyl acceptor) to generate N-acyl phosphatidylethanolamine (NAPE). Similarly can use plasmenylethanolamine as a fatty acyl acceptor to form N-acyl plasmenylethanolamine (N-Acyl-PlsEt). Both NAPE and N-Acyl-PlsEt can serve as precursors of bioactive NAEs like N-arachidonoyl phosphatidylethanolamine also called anandamide. Has weak phospholipase A2 and lysophospholipase activities (By similarity). Regulates intracellular membrane trafficking that requires modulation of membrane curvature as it occurs by enrichment in lysophospholipids. Promotes tubule formation involved in clathrin-independent endocytotic trafficking and cargo recycling (By similarity).
Synonyms: FLJ45651
Tractability: Antibody: UniProt places it where antibodies can reach, with medium confidence; its Gene Ontology location is reachable by antibodies, with medium confidence.
Target class: Enzyme; Hydrolase
Gene: Protein-coding gene on chromosome 15 (41,981,394 to 42,051,190, reverse strand). Ensembl gene ENSG00000188089.
Subcellular location: Cytoplasm, cytosol; Early endosome membrane; Lysosome membrane; Cell membrane
Subcellular location (Human Protein Atlas): Cytosol; Vesicles
Pathways (Reactome):
Metabolism: Acyl chain remodelling of PC; Acyl chain remodelling of PE; Acyl chain remodelling of PI; Acyl chain remodelling of PS; Hydrolysis of LPC
Gene Ontology:
Molecular function: acyltransferase activity, transferring groups other than amino-acyl groups; calcium ion binding; calcium-dependent phospholipid binding; phosphatidylinositol-3,4,5-trisphosphate binding; phosphatidylinositol-3,4-bisphosphate binding; phosphatidylinositol-3,5-bisphosphate binding; phosphatidylinositol-3-phosphate binding; phosphatidylinositol-4,5-bisphosphate binding; phosphatidylinositol-4-phosphate binding; phosphatidylinositol-5-phosphate binding; phospholipase A1 activity; phospholipase A2 activity; phospholipase activity
Biological process: N-acylphosphatidylethanolamine metabolic process; positive regulation of endocytic recycling; glycerophospholipid catabolic process; phosphatidylinositol acyl-chain remodeling; glycerophospholipid metabolic process; phospholipid catabolic process
Cellular component: cytosol; early endosome membrane; lysosomal membrane; plasma membrane
Genetic constraint (gnomAD): Loss-of-function variants: 84 observed, 100.14 expected, observed/expected ratio (o/e) 0.84, 90% interval 0.7 to 1.01. The upper end of that interval is the gene's LOEUF score, 1.01, which puts it in group 4 of 6, group 1 being the genes least tolerant of losing a copy. Missense variants: 1,049 observed, 1,061.7 expected, observed/expected ratio (o/e) 0.99, 90% interval 0.94 to 1.04. Synonymous variants: 465 observed, 428.49 expected, observed/expected ratio (o/e) 1.09, 90% interval 1 to 1.17.
Homologues: Orthologues: macaque PLA2G4E (97% identical), chimpanzee PLA2G4E (97% identical), dog PLA2G4E (83% identical), pig PLA2G4E (82% identical), rabbit PLA2G4E (82% identical), rat Pla2g4e (78% identical), mouse Pla2g4e (77% identical), guinea pig PLA2G4E (77% identical), tropical clawed frog pla2g4d (42% identical), tropical clawed frog jmjd7-pla2g4b (35% identical), zebrafish pla2g4f.2 (34% identical), zebrafish pla2g4f.1 (33% identical). Paralogues in human: PLA2G4D (43% identical), PLA2G4B (40% identical), PLA2G4F (38% identical), PLA2G4A (27% identical), PLA2G4C (15% identical).
Diseases named in the same sentence as PLA2G4E in open-access papers:
PLA2G4E is named in the same sentence as 14 diseases in open-access papers, as found by Europe PMC text mining. Sharing a sentence is not in itself a finding about the gene and the disease. The quoted sentences say what the papers report.
panic disorder (3 papers, 2018 to 2025). An anxiety disorder characterized by multiple unexpected panic attacks with persistent concern of recurring attacks. "Whole-exome sequencing has identified PLA2G4E as a risk gene for panic disorder, a neuropsychiatric disease characterized by recurrent and unexpected panic attacks, subsequent anticipatory anxiety, and phobic avoidance." (PMID 40244184, 2025). "Furthermore, genetic variants within the PLA2G4E gene have been suggested as plausible risk factors for neurodevelopmental issues, notably including panic disorder." (PMID 40634107, 2025). "Furthermore, genetic and epigenetic variants within the PLA2G4E gene have been associated with potential risks for neurodevelopmental disorders, such as panic disorder, and atypical neurobehavior in preterm infants." (PMID 40634107, 2025).
dementia (2 papers, 2021 to 2025). Loss of intellectual abilities interfering with an individual's social and occupational functions. "Taking into account our previous success on identifying PLA2G4E overexpression as a novel therapeutic strategy for AD by studying cognitive resilient individuals, here we performed a similar study to try to better understand the mechanisms underlying dementia resilience in AD." (PMID 34502030, 2021). "Future studies should investigate whether critical conditions, such as the accumulation of age-related changes or exacerbation of Alzheimer’s disease neuropathology, could hasten the onset of dementia in the absence of PLA2G4E." (PMID 40634107, 2025).
melanoma (2 papers, 2023 to 2025). A malignant, usually aggressive tumor composed of atypical, neoplastic melanocytes. "Risk forest plot analysis revealed that SFN, PLA2G4E, SERPINB5, WWC1, PAK6, and TEAD3 were the most influential genes in promoting melanoma malignancy." (PMID 41034991, 2025). "To predict the prognosis of melanoma patients, we calculated the risk score of each patient based on the expression and corresponding lambda value of seven genes (PLA2G2D, FUT8, PLA2G4E, PLA2G5, PLA2G1B, B3GNT2, and ST3GAL5)." (PMID 37205993, 2023).
Obesity (2 papers, 2020 to 2025). Accumulation of substantial excess body fat. "Moreover, the PLA2G4E gene in its locus has been previously associated with both obesity and CVD." (PMID 41373836, 2025). "In addition, the disruption of the PLA2G4E-regulated pathway can cause obesity." (PMID 32138348, 2020).
Alzheimer disease (1 paper, 2025). A progressive, neurodegenerative disease characterized by loss of function and death of nerve cells in several areas of the brain leading to loss of cognitive function such as memory and language. "Given its potential role in supporting cognitive resilience, PLA2G4E has emerged as a compelling therapeutic target in the context of Alzheimer’s disease (AD)." (PMID 40634107, 2025).
cognitive disorders (1 paper, 2025). A disease affects cognitive processes. "Collectively, our findings highlight PLA2G4E as a critical regulator of brain maturation, with its dysfunction potentially contributing to neurodevelopmental and cognitive disorders." (PMID 40634107, 2025).
colorectal cancer (1 paper, 2020). A primary or metastatic malignant neoplasm that affects the colon or rectum. "The PLA2G4E gene was reported to be highly expressed in visceral adipose tissue in colorectal cancer patients and participated in lipid metabolism." (PMID 32138348, 2020).
diabetes (1 paper, 2016). "For example, in subjects with prediabetes versus controls, cytochrome P450, family 4, subfamily F, polypeptide 3 (CYP4F3), CYP4F8, Phospholipase A2, group IIC (PLA2G2C), and PLA2G4E were differentially methylated, while in subjects with diabetes versus prediabetes, CYP2E1 and PLA2G12A were involved." (PMID 27555869, 2016).
psoriasis (1 paper, 2021). An autoimmune condition characterized by red, well-delineated plaques with silvery scales that are usually on the extensor surfaces and scalp. "Among the overlapping PRP and psoriasis DEGs were several psoriasis hallmark genes, including proinflammatory cytokines and chemokines, skin barrier–related genes, and several PLA2 family genes (PLA2G2F, PLA2G4D, and PLA2G4E)." (PMID 34491907, 2021). "This led to our identification of 3 members of the PLA2 family, both soluble (PLA2G2F) and cytoplasmic (PLA2G4D and PLA2G4E), as a critical pathogenic pathway shared between PRP and psoriasis." (PMID 34491907, 2021). "The major common pathway shared between psoriasis and PRP involves the phospholipases PLA2G2F, PLA2G4D, and PLA2G4E, which were found to be primarily expressed in the epidermis." (PMID 34491907, 2021). "Here, we show that PLA2G2F (sPLA2) and PLA2G4D/PLA2G4E (cPLA2s) are highly expressed in the epidermis of both PRP and psoriasis." (PMID 34491907, 2021).
Sepsis (1 paper, 2025). Sepsis is defined as life-threatening organ dysfunction caused by a dysregulated host response to infection. "Rare variants in LTBP4 are significantly associated with the most severe pediatric sepsis phenotype (PedSep-D), while variants in PLA2G4E and CCDC157 show associations with this phenotype in suggestive significance." (PMID 41076474, 2025).
carcinoma (1 paper, 2022). A malignant tumor arising from epithelial cells. "In the IHC data of HPA, there is a lack of carcinoma or corresponding normal tissues of several candidate genes includingSDR9C7,RDH12,RAET1E,CERS3,PLA2G4E,CYP4F22, andDENND2C." (PMID 36017889, 2022).
metabolic disease (1 paper, 2022). A congenital disorder (due to inherited enzyme abnormality) or acquired (due to failure of a metabolically important organ) disorder resulting from an abnormal metabolic process. "PLA2G4E is one of the important members of the PLA2 family, and it regulates skeletal muscle and metabolic diseases." (PMID 36139132, 2022).
tumor (1 paper, 2024). "We identified 9 genes whose increased expression was significantly associated with tumor size in female LC patients of which four code for MAPK signaling molecules (DUSP4, FGL1, TXNRD1, PLA2G4E), three for oncogenes (KRT16, STRIP2 and TNS4), tumor suppressor cystatin 5, and NQO1." (PMID 38245882, 2024).
PLA2G4E also shares sentences with these, for which no sentence is quoted: prediabetes (1 paper).